IRF3 (interferon regulatory factor 3)
Diseases named in the same sentence as IRF3 in open-access papers (continued):
Sharing a sentence is not in itself a finding about the gene and the disease.
asthma (8 papers, 2014 to 2025). "Increased IRF1 and IRF3 expression might take part in GLCCI1 deficiency-induced GC insensitivity in asthma." (PMID 34504850, 2021). "In our study, the levels of TLR3, p-P65, p-IκBα, and IRF3 were clearly increased in lung tissues of asthma mice and LPS-mediated 16HBE cells." (PMID 36213326, 2022). "Furthermore, studies have also revealed the important role of the TLR3/NF-κB/IRF3 signaling pathway in the progression of viral-induced asthma." (PMID 40672946, 2025). "Moreover, some researchers have demonstrated the crucial role of the TLR3/NF-κB/IRF3 signaling pathway, which is activated by the inflammatory cytokines during the progress of virus-induced asthma." (PMID 36213326, 2022). "Interestingly, the expression of IRF3 by DCs was found to be critical for their optimal maturation, and for the development of asthma in similar models." (PMID 29201030, 2017). "This study highlights an important interaction between IL-17A and TLR3 signaling in excessive airway inflammation, and control of IL-17A/TLR3-mediated NF-κB/IRF3 activation may be a novel therapeutic target to prevent exacerbation of asthma." (PMID 26418032, 2015). "Besides, more detailed basic and clinical investigations through systemic inhibition studies such as knock-down or knock-out models are required to assess whether overexpression of TLR3/NLRP3/NF-κB/IRF3 signaling could reverse the protective effect of CAD on asthma." (PMID 36213326, 2022). "Therefore, we are devoted to exploring the effects of CAD on pyroptosis and the TLR3/NLRP3/NF-κB/IRF3 signaling pathway in OVA/RSV-induced asthma mouse models, which may contribute to promoting understanding of CAD in the treatment of acute asthma with RSV infection." (PMID 36213326, 2022). "This project determines the underlying mechanism that GLCCI1 deficiency attenuates GC sensitivity in dexamethasone (Dex)-treated Ovalbumin (OVA)-induced asthma mice and epithelial cells through upregulating binding of IRF1:GRIP1 and IRF3:GRIP1." (PMID 34504850, 2021). "The present project confirms that the loss of GLCCI1 expression leads to GC insensitivity through downregulating the GR-GRIP1 pathway, which is associated with the increased interaction between IRF1 and GRIP1 and between IRF3 and GRIP1 in asthma." (PMID 34504850, 2021). "Generally, these results indicated that apoptosis and pyroptosis played an important role in RSV-infected asthma mice and LPS-mediated 16HBE cells, and CAD potential inhibits the TLR3/NLRP3/NF-κB/IRF3 signaling pathway and subsequently suppresses airway inflammation and pyroptosis." (PMID 36213326, 2022). "For this reason, NLRP3 which regulates pyroptosis-induced asthma requires to be further studied, and TLR3/NLRP3/NF-κB/IRF3 signaling inhibition could be an anti-inflammatory strategy in airway epithelial injury." (PMID 36213326, 2022). "However, the induction of several interferon-related genes (IRF3, IFNAR1, IFNB1, IFNGR1, IL28B) was impaired in patients with asthma." (PMID 24475887, 2014). "Among the genes that were induced in all subjects except for patients with asthma were interferon involved genes (IL28B, IFNAR1), CCL22, and FOSL1 with respect to the upper airways, and several interferon involved genes (IRF3, IFNAR1, IFNB1, IFNGR1, IL28B) in the lower airways." (PMID 24475887, 2014). "Additionally, CAD and CAD-contained serum attenuated the up-regulated expressions of Bax, Cleaved caspase-3, NLRP3, ASC, Cleaved caspase-1, GSDMD-N, IL-18, IL-1β, TLR3, p-P65, p-IκBα, and IRF3 but increased Bcl-1 and GSDMD levels in the asthma mice and LPS-induced 16HBE cells, respectively." (PMID 36213326, 2022).
co-infection (8 papers, 2010 to 2024). "Paradoxically, the slow-replicating T3DTD phenodominantly induced IRF3 activation during co-infection with fast-replicating T3DPL, despite that T3DPL phenodominantly produced high levels of virus proteins." (PMID 32956403, 2020). "To distinguish these possibilities, we reasoned that viruses containing a direct inhibitor of IFN production (e.g. a viral protein that sequesters IRF3) should be able to prevent IFN production during co-infection and rescue kin viruses devoid of the activity." (PMID 32956403, 2020). "Studies utilizing a co-infection model or an inducible ICP0 expression model provide contradictory evidence regarding the ability of ICP0 to block IRF3 activation by an exogenous source." (PMID 20454685, 2010). "However, it has been demonstrated by others, as well as us, that IRF3 was modulated in the context of viral co-infection at the initial moments of infection." (PMID 34310619, 2021). "Interestingly, co-infection with ISVPs could block the nuclear accumulation of IRF3 in a time dependent manner." (PMID 28883463, 2017). "Distinctly, VL1 patient, that has disorganized spleen and VL-HIV coinfection was related to SOD1, STAT3, STAT4, ICOS, TRAF6 and IRF3 genes, and CD8+ cells in the RP and expression of IL6 in both regions of spleen." (PMID 38843306, 2024). "Paradoxically, during co-infections by T3DPL and T3DTD, there was still high IRF3 phosphorylation indicating a phenodominant effect by the slow-replicating T3DTD." (PMID 32956403, 2020). "Whereas in a SeV co-infection model, ICP0 appeared to elicit IRF3 degradation, we failed to observe degradation of any known components of the IRF3 pathway in the context of an HSV-1 infection." (PMID 20454685, 2010). "Studies employing a co-infection model with HSV-1 and Sendai virus (SeV) found that ICP0 inhibited IRF3 nuclear translocation and mediated its degradation." (PMID 20454685, 2010). "It is also unexpected that robust replication of T3DPL during co-infections failed to prevent IRF3 phosphorylation by T3DTD in co-infected cells; this suggests it is unlikely that T3DPL globally counteracts RIG-I signalling." (PMID 32956403, 2020). "However, the virion-mediated inhibition of IRF3 nuclear translocation was less pronounced and delayed compared to ISVP co-infection." (PMID 28883463, 2017). "Additionally, an inhibitor of IRF-3-dependent gene transcription diminished the IL-12p70 secretion after bacterial infection or viral/bacterial co-infection showing that IRF-3 plays a large role in the production of IL-12p70 in this co-infection system." (PMID 23421931, 2013). "Phospho-IRF3 levels were similar between T3DTD and T3DPL/T3DTD co-infection, suggesting that T3DTD-dependant activation of IRF3 could not be overcome by the presence of T3DPL." (PMID 32956403, 2020). "Importantly, regardless of the MOI, the levels of phosphor-IRF3 were determined by T3DTD dose (and not T3DPL dose) during T3DPL-T3DTD co-infections." (PMID 32956403, 2020).
leukemia (8 papers, 2017 to 2023). A malignant (clonal) hematologic disorder, involving hematopoietic stem cells and characterized by the presence of primitive or atypical myeloid or lymphoid cells in the bone marrow and the blood. "Functional studies in fibroblasts and human leukemia monocytic THP1 cells showed that both variants individually suppressed TLR3-driven IRF3 transcriptional activity and the type I IFN response in vitro." (PMID 37097753, 2023). "In parallel, there is a report of DNA-PK activating an STING-independent pathway to IRF3 activation in a human leukemia cell line." (PMID 38269102, 2023). "cGAMP and ISD induced nuclear translocation of endogenous IRF3 and expression of IRF3 target genes in TRAMP-C2 and THP-1 leukemia cells." (PMID 33790360, 2021). "It has been demonstrated that MSA-2 can activate mouse and human STING genes, induce the phosphorylation of TBK1 and IRF-3 and activate the STING signal pathway in the human leukemia monocytic cell line (THP-1 cells) and induce the expression of IFN-β, IL-1β and TNF-α via the action of TBK1." (PMID 38005816, 2023). "However, as the loss of STING did not completely abrogate autophagy inhibitor-mediated cytotoxicity in leukemia cells, the contribution of STING-independent activation of IRF3 cannot be excluded." (PMID 33771977, 2021). "One study found that in the leukemia cell line THP-1, CHK1i increased TBK1 but did not increase IRF3 phosphorylation, induce IRF3 or NF-κB reporter activation, nor induce a type 1 IFN response." (PMID 36276148, 2022).
ovarian carcinoma (8 papers, 2015 to 2025). A malignant neoplasm originating from the surface ovarian epithelium. "This dysregulation likely contributes to immune evasion, allowing cancer cell proliferation without triggering antiviral and anti-tumor responses, highlighting the potential of STING/IRF3 modulation for restoring immune surveillance in ovarian cancer." (PMID 39949780, 2025). "The STING/IRF3 pathway, crucial for innate immune responses to foreign DNA, is dysregulated in ovarian cancer." (PMID 39949780, 2025). "Normalizing p-IRF3 levels to total IRF3 indicated that there was little change in IRF3 activation in the ovarian cancer cells." (PMID 25658875, 2015). "We first selected 3 SLFN11-deficient (EFO-21, KURAMOCHI, RMGI, SLFN11–) and 3 SLFN11-proficient (OAW42, OV7 and OV-56, SLFN11+) ovarian cancer cell lines that were all STING pathway proficient, as illustrated by cGAS and IRF3 expression." (PMID 34549724, 2021). "Our preliminary data have shown that the POL I inhibitor CX-5461 induces a significant accumulation of cytosolic DNA, transcriptionally activates STING, and induces phosphorylation of IRF3, which induces type I IFN in ovarian cancer cells." (PMID 34680204, 2021). "In contrast to T80 and HMEC cells, we did not observe increases in PLSCR1 expression (or p-IRF3) in ovarian cancer cell lines, despite similar transfection efficiencies between T80 and the ovarian cancer cell lines (HEY, TOV21G, and TOV112D)." (PMID 25658875, 2015). "However, in ovarian cancer cells, dsDNA transfection fails to trigger IRF3 phosphorylation or PLSCR1 induction, suggesting immune evasion by suppressing the STING/IRF3 pathway." (PMID 39949780, 2025). "Furthermore, the phosphorylation levels of TBK1, P65, and IRF3 were significantly elevated in ovarian cancer cells and normal immortalized ovarian epithelial cells treated by both PARPi and Entinostat, indicating the activation of cGAS-STING pathway." (PMID 37063431, 2023). "Interestingly, we noted an increase in STING and STAT1 levels only in T80 cells and not in ovarian cancer cells upon dsDNA transfection suggesting that the absence of IRF3 activation could be due to an altered upstream signaling involving STING and STAT1." (PMID 25658875, 2015). "In contrast to normal T80/HMECs, the phosphorylation of IRF3 as well as induction of STING and PLSCR1 were absent in ovarian cancer cells (serous, clear cell, and endometrioid) suggesting that the STING/IRF3 pathway may be dysregulated in these cancer cells." (PMID 25658875, 2015).
pneumonia (8 papers, 2021 to 2026). An acute, acute and chronic, or chronic inflammation focally or diffusely affecting the lung parenchyma, caused by an infection in one or both of the lungs (by bacteria, viruses, fungi, or mycoplasma.). "In Baladi goats with pneumonia and healthy control group, PCR-DNA sequencing revealed SNPs linked to pneumonia susceptibility and resistance in immunological genes (SLC11A1, CD-14, CCL2, TLR1, TLR7, TLR8, TLR9, defensin, SP110, SPP1, BP1, A2M, ADORA3, CARD15, IRF3, and SCART1)." (PMID 40221769, 2025). "The immune genes’ mRNA levels in goats (SLC11A1, CD-14, CCL2, TLR1, TLR7, TLR8, TLR9, defensin, SP110, SPP1, BP1, A2M, ADORA3, CARD15, IRF3, and SCART1) varied between the healthy and infected goats with pneumonia." (PMID 40711280, 2025). "Through PCR-DNA sequencing in Baladi goats with and without pneumonia, SNPs linked to pneumonia susceptibility and resistance were discovered in the immunological (SLC11A1, CD-14, CCL2, TLR1, TLR7, TLR8, TLR9, defensin, SP110, SPP1, BP1, A2M, ADORA3, CARD15, IRF3, and SCART1) genes." (PMID 40711280, 2025). "The levels of immunological genes (SLC11A1, CD-14, CCL2, TLR1, TLR7, TLR8, TLR9, defensin, SP110, SPP1, BP1, A2M, ADORA3, CARD15, IRF3, and SCART1) vary in goats with and without pneumonia." (PMID 40221769, 2025). "Real-time PCR was conducted to quantify the expression levels of immunological markers (SLC11A1, CD-14, CCL2, TLR1, TLR7, TLR8, TLR9, β defensin, SP110, SPP1, BP1, A2M, ADORA3, CARD15, IRF3, and SCART1) in Baladi goats with and without pneumonia resistance." (PMID 36977224, 2023).
rheumatoid arthritis (8 papers, 2014 to 2024). A chronic, systemic autoimmune disorder characterized by inflammation in the synovial membranes and articular surfaces. "Unregulated levels of IRF3 and the type-IFNs have been implicated in tumorigenesis and progression of autoimmune disorders including rheumatoid arthritis (RA), SLE and primary Sjogren’s syndrome." (PMID 33633536, 2021). "TRIM3 overexpression has an inhibitory effect on the proliferation and cytokine secretion of fibroblast-like synoviocytes in rheumatoid arthritis and can protect against LPS-induced acute kidney injury by inhibiting the IRF3 pathway and NLRP3 inflammasome activation." (PMID 37520369, 2023).
Autoimmunity (7 papers, 2009 to 2025). The occurrence of an immune reaction against the organism's own cells or tissues. "The resulting increase in STING activity causes activation of interferon regulatory factor 3 (IRF3), potentiating type I IFN secretion and exacerbating autoimmunity in response to UV exposure." (PMID 30405625, 2018). "TREX1 deficient cells accumulate cytoplasmic DNA derived from endogenous retroelements, which can then activate IRF3 to trigger production of type I IFNs leading to autoimmunity." (PMID 19266025, 2009). "Our study further reveals that transcriptional regulators such as IRF3, IRF7, STAT1, and MYB are critically involved in T cell-mediated autoimmunity, along with ncRNAs LINC00487, LINC01260, and MIR223 with their expression patterns linked to immune dysregulation." (PMID 39844998, 2025).
inflammatory bowel disease (7 papers, 2012 to 2025). A spectrum of small and large bowel inflammatory diseases of unknown etiology. "In inflammatory bowel disease (IBD), IRF3 and IRF7 are upregulated in the intestinal mucosa, promoting localized inflammation." (PMID 41383611, 2025). "TRIM21 also influences T cell differentiation by targeting IRF3 to inhibit ex vivo Th1 and Th17 differentiation in CD4+ T cells isolated from inflammatory bowel disease (IBD) patients." (PMID 30741923, 2019).
kidney infection (7 papers, 2010 to 2025). "The susceptibility to kidney infection is increased in mice carrying deletions in the interferon regulatory factor 3 gene (Irf3) and Irf3−/−mice provide a relevant model of human disease." (PMID 40000737, 2025). "Irf3−/− mice are highly susceptible to kidney infection and develop acute pyelonephritis, with high bacterial counts and excessive innate immune activation, leading to abscess formation." (PMID 38251349, 2023). "Work in humans has identified genetic factors that confer susceptibility to pyelonephritis and renal scarring, including polymorphisms reducing IRF3 or CXCR1 (encoding IL-8 receptor) expression, in certain UTI-prone kindreds." (PMID 33513212, 2021). "Based on the phenotype of IRF3 knockout mice, the authors predicted that reduced IRF3 expression could also increase human susceptibility to severe kidney infection." (PMID 35860746, 2022). "The phenotype of Irf3−/− mice predicted that reduced IRF3 expression could also increase human susceptibility to severe kidney infection." (PMID 20886096, 2010). "Finally, in highly disease-prone pyelonephritis patients we found a high frequency of IRF3 promoter polymorphism compared to asymptomatic bacterial carriers or controls." (PMID 20886096, 2010). "The genetic and functional studies described here indicate that genetic variation in IRF3 influences individual susceptibility to kidney infection and might serve as a new tool for future risk assessment in this patient group." (PMID 20886096, 2010). "Moreover, recently described new IRF3 signaling indicates that the genetic variation in IRF3 influences individual susceptibility to the kidney infection and might serve as a new tool for future risk assessment in this patient group." (PMID 22506110, 2012). "Fischer and coauthors showed that IRF3 knockout mice develop severe acute pyelonephritis and extensive renal tissue damage in experimental UTI." (PMID 35860746, 2022). "Relevance of IRF3 pathway for human disease was supported by data concerning polymorphic IRF3 promoter sequences, which differ between children with severe, symptomatic kidney infection and children who were asymptomatic bacterial carriers." (PMID 22506110, 2012). "Relevance of this pathway for human disease was supported by polymorphic IRF3 promoter sequences, differing between children with severe, symptomatic kidney infection and children who were asymptomatic bacterial carriers." (PMID 20886096, 2010). "Irf3−/− mice lacking this pathway, developed rapid lethal kidney infections with extensive tissue damage and patients prone to acute pyelonephritis were shown to carry IRF3 promoter polymorphisms that reduce transcription efficiency." (PMID 20886104, 2010). "Furthermore, we show that IRF3 dependent innate immunity is essential for the host defense, as Irf3 knockout mice develop severe kidney infection." (PMID 20886096, 2010). "Thus, IRF3 may be a new molecular target in the diagnosis of UTI susceptibility, potentially creating more precise approaches for detection and prevention of severe, recurrent kidney infection and associated debilitating morbidity." (PMID 20886096, 2010).
Listeria infection (7 papers, 2009 to 2025). "We found that ferrous iron treatment and FPN1 deficiency both attenuated Listeria monocytogenes infection-induced phosphorylation of IRF3 and TBK1 and the expression of IFN-β and proinflammatory cytokines in macrophages." (PMID 40595467, 2025). "In contrast, it was shown that type I IFNs are detrimental to the host during listeriosis and IRF3−/−, IFNβ−/− or IFNAR−/− mice show an enhanced resistance to L. monocytogenes challenge." (PMID 21179567, 2010). "We assume that mDC produce low amounts of IFNβ immediately after Listeria infection in an IRF3-dependent manner." (PMID 19325882, 2009). "An IRF3 polymorphism in mice alters induction of IFN-β response and affects resistance to Listeria infections." (PMID 19432955, 2009). "Listeria monocytogenes infection induces a potent host type I IFN response mediated by the Tbk1 kinase and Irf3." (PMID 19578435, 2009).